SP3 (Sp3 transcription factor)
Diseases named in the same sentence as SP3 in open-access papers (continued):
Sharing a sentence is not in itself a finding about the gene and the disease.
prostate carcinoma (12 papers, 2009 to 2024). A carcinoma that arises from epithelial cells of the prostate gland. "The transcription factor Sp3 regulates BNIP3 to inhibit the proliferation of prostate cancer cells and cause apoptosis." (PMID 34853602, 2021). "Specificity protein (Sp) transcription factors (Sp1/Sp3/Sp4) are often overexpressed in colon cancer, pancreatic cancer, bladder cancer, breast cancer, prostate cancer, and many other cancers." (PMID 32851058, 2020). "In experiments to understand the role of FLIP regulation during prostate carcinogenesis, we identified transcription factors Sp1 and Sp3 as important regulators of FLIP transcriptional activity in prostate cancer cells." (PMID 23028678, 2012). "It is noteworthy that we previously showed that Sp1 trans-activates FLIP in prostate cancer cells, whereas Sp3 inhibits this trans-activation." (PMID 23028678, 2012). "Previous studies in this laboratory showed that BA inhibits prostate cancer cell and tumor growth and this is accompanied by proteasome-dependent degradation of Sp1, Sp3 and Sp4 and several Sp-regulated pro-oncogenic gene products." (PMID 21864401, 2011). "Studies in this laboratory show that BA inhibits prostate cancer cell and tumor (xenograft) growth and this is due, in part, to proteasome-dependent downregulation of Sp1, Sp3, Sp4 and several Sp-regulated genes." (PMID 21864401, 2011). "Similarly, ZBTB4 can transcriptionally inhibit specific protein transcription factors (Sp1, Sp3, and Sp4), thereby inhibiting the proliferation of prostate cancer cells and promoting cell apoptosis." (PMID 34047477, 2021). "Our data suggest that FLIP expression could be positively regulated by Sp1 in tumor cells and that targeting Sp1/Sp3/FLIP could be a potential avenue for clinical management of recurring prostate cancer." (PMID 23028678, 2012). "In this study we assessed the expression of the anti-apoptotic protein FLIP and the transcription factors Sp1 and Sp3 by immunohistochemical evaluation of tissue samples obtained from 64 patients who underwent radical prostatectomy as primary treatment for prostate cancer." (PMID 23028678, 2012). "In this study we assessed the expression of the anti-apoptotic protein FLIP and its transcription regulators Sp1 and Sp3 by immunohistochemical evaluation of tissue samples obtained from 64 patients who underwent radical prostatectomy as primary treatment for prostate cancer." (PMID 23028678, 2012). "Increased levels of Sp1/Sp3/FLIP might be related to apoptotic resistance and progression to biochemical recurrence or progression from low- to high-risk prostate cancer." (PMID 23028678, 2012). "In summary, our data indicate that the Sp1/Sp3/FLIP signature in combination with Gleason grade is predictive of recurrence of prostate cancer and that its clinical application might avoid unnecessary aggressive interventions, thus improving quality of life and reducing healthcare related expenses." (PMID 23028678, 2012). "Previous work in prostate cancer cells similarly showed DHT-induced suppression of GPER that occurs through androgen receptor binding to transcription factors Sp1 and Sp3 and prevent their transcription of GPER." (PMID 36798163, 2023). "Recently, transcription factors Sp1, Sp3 and Egr-1 have been identified as potent regulators of MT1-MMP expression in prostate cancer, endothelial and glomerular mesangial cells." (PMID 21176152, 2010). "This phenomenon was also observed in prostate cancer PC-3 cells, indicating that the transcriptional role of Sp3 for the AFAP1L1 gene is not restricted to sarcoma cells." (PMID 23326307, 2013). "The observation that Sp1/Sp3 and FLIP may be predictors of clinical outcome could reflect their important role in prostate cancer." (PMID 23028678, 2012).
glioma (9 papers, 2009 to 2025). A benign or malignant brain and spinal cord tumor that arises from glial cells (astrocytes, oligodendrocytes, ependymal cells). "Genes positively correlated with ZNF800 play crucial roles in LGG pathology; for example, SP3 can indirectly induce glioma proliferation and metastasis, play a key role in the malignant biological behavior of gliomas, and lead to poor prognosis for patients." (PMID 40644416, 2025). "In a subsequent study, the high MAO-B expression demonstrated a positive correlation with the tumor grade, the transcription factor Sp3 and HIF1α, the latter being localized in the nuclei in advanced gliomas or in the cytosol in low-grade gliomas." (PMID 39714760, 2025). "Sp3 is functionally regulated by SUMOylation, and SENP3 mediates the deSUMOylation of Sp3 in glioma." (PMID 33192553, 2020). "To identify which transcription factor is a potent regulator for CYP17A1 transcription in glioma, we analyzed the correlation of CYP17A1 with NFIC, Sp1, Sp3 or GATA6 in complementary DNA microarray database of glioma." (PMID 28530704, 2017). "This inversion of function, with Sp3 repressing MAOB transcription in GBM and activating it in the astrocytic glioma, may be linked to SUMOylation changes in these glioma, and such a change appears to be linked to tumor grade." (PMID 26689994, 2016). "In research, it was found that the epidermal growth factor receptor activation in the glioma is induced by COX-2 (cyclooxygenase 2-self-dependent prognostic factor in glioma) expression, through P38 mitogen activation of SP1/SP3." (PMID 37298889, 2023).
bladder cancer (6 papers, 2011 to 2025). "In contrast, EV samples derived from both GCB‐sensitive and GCB‐resistant bladder cancer cell lines, including SP3 (T24 EVs), SP4 (T24GCB EVs), SP5 (5637 EVs) and SP6 (5637GCB EVs), showed no detectable GCB signal." (PMID 41159684, 2025). "Arsenic trioxide also induced caspase-dependent cleavage of Sp3 and Sp4 in bladder cancer cells and retinoid (CD437)-induced Sp1 degradation was also caspase-dependent in EL-4 cells." (PMID 23110215, 2012). "ROS and hydrogen peroxide (H2O2) play a role in downregulation of Sp1, Sp3 and Sp4 in pancreatic and bladder cancer cells and treatment of RKO cells with BA for 36 h induced ROS as determined by FACS analysis using the fluorescent ROS scavenger H2DCFDA." (PMID 21864401, 2011). "Previous studies showed that BA-induced downregulation of Sp1, Sp3 and Sp4 was proteasome-dependent in LNCaP cells but proteasome-independent in KU7 bladder cancer cells." (PMID 21864401, 2011). "Previous studies demonstrated high specificity for knockdown of Sp1, Sp3 and Sp4 by RNAi in RD rhabdomyosarcoma and KU7 bladder cancer cells, whereas in other cell lines, knockdown of an individual Sp protein also decreased expression of one or both of the other gene products." (PMID 26967243, 2016). "For example, knockdown of Sp1 (siSp1) or Sp3 (siSp3) in 253JB-V bladder cancer cells decreased expression of Sp4 protein, whereas siSp4 did not affect levels of Sp3 or Sp1 proteins." (PMID 26967243, 2016).
gastric cancer (5 papers, 2013 to 2023). A primary or metastatic malignant neoplasm involving the stomach. "Furthermore, Sp1 expression, but not Sp3, was frequently downregulated in gastric cancer compared with normal gastric mucosa, which was associated with a paralleled reduction in SHIP2 levels in gastric cancer." (PMID 28117748, 2017).
hepatocellular carcinoma (5 papers, 2018 to 2024). A malignant tumor that arises from hepatocytes. "High expression of SP3 was observed in hepatocellular carcinoma tissues compared with control tissues." (PMID 36553500, 2022). "Therefore, we speculate that ZBP-89 and Sp1/Sp3 are involved in hepatocellular carcinoma (HCC) and Bak induction." (PMID 29653560, 2018).
lung carcinoma (5 papers, 2012 to 2024). "Only few direct transcriptional regulators of DNMT3B such as SP1, SP3 or FOXO3A have been identified and only few that are known have such a clear and important link to cancer (for example, FOXO3A negatively regulates DNMT3B promoter activity in lung cancer)." (PMID 29100357, 2017). "Although studies on Sp3 and cancer are lacking, Sp1 levels have been shown to be elevated in a wide variety of cancers including breast, thyroid, hepatocellular, pancreatic, colorectal, gastric, and lung cancer." (PMID 23028678, 2012). "SP3, which belongs to the SP family, is a non-oncogene addiction (NOA) gene and drug target in human cancers, including lung cancer." (PMID 38354174, 2024).
colorectal cancer (4 papers, 2018 to 2025). A primary or metastatic malignant neoplasm that affects the colon or rectum. "IL-4 induced STAT6 signaling in promoting cell proliferation/growth and cell apoptosis resistance and induced epithelial-mesenchymal transition (EMT) in colorectal cancer cells via E2F1/SP3/STAT6 axis." (PMID 33506057, 2021).
respiratory failure (4 papers, 2010 to 2023). The significant impairment of gas exchange within the lungs resulting in hypoxia, hypercarbia, or both, to the extent that organ tissue perfusion is severely compromised. "While the role of Sp3 in the lung is unclear, Sp3-deficient embryos are growth retarded and invariably die at the birth of respiratory failure." (PMID 37166104, 2023). "Sp3-deficient mice display skeletal, tooth, hematopoietic and heart defects at late embryonic development, and die immediately after birth due to respiratory failure." (PMID 21085687, 2010). "However, on a mixed C57BL/6 and 129/Ola background, SP3-null mice survived until birth and died from respiratory failure." (PMID 32499402, 2020). "The role of Sp1 in nociception is unstudied as null mice completely lacking Sp1 die early in embryogenesis, whereas, Sp3 -/- null mice are growth-retarded and die at birth due to respiratory failure." (PMID 21645329, 2011).
rhabdomyosarcoma (4 papers, 2016 to 2024). A rare aggressive malignant mesenchymal neoplasm arising from skeletal muscle. "Studies on normal cell transformation into cancer cell lines show that this transformation process is accompanied by increased levels of Sp1 in most cell models, and in the transformation of muscle cells into rhabdomyosarcoma, both Sp1 and Sp3, but not Sp4, are increased." (PMID 36982239, 2023). "Rhabdomyosarcomas (RMS) express high levels of Sp1 compared to non-transformed muscle tissue and RMS cell lines express high levels of Sp1, Sp3 and Sp4." (PMID 36982239, 2023). "Inhibition of SP family (SP1, SP3 and SP4) could suppress rhabdomyosarcoma cell and tumor growth via non-steroidal anti-inflammatory drug (NSAID) tolfenamic acid (TA)." (PMID 35847857, 2022).
lymphoma (3 papers, 2016 to 2021). A malignant (clonal) proliferation of B- lymphocytes or T- lymphocytes which involves the lymph nodes, bone marrow and/or extranodal sites. "Interestingly, perusal of the Catalogue of Somatic Mutations in Cancer (COSMIC) database revealed that PHIP and SP3 are found mutated in other human cancers, including a small fraction of hematopoietic and lymphoid cancers." (PMID 27982060, 2016). "The restoration of SP3 expression has been proposed to suppress the cancer phenotype of lymphoma cells." (PMID 36618443, 2021). "The results of this study shows that both Sp3 and Phip behave as tumor suppressors in Eμ-Myc driven lymphomas." (PMID 35154242, 2021). "In sum, our results demonstrate that both Sp3 and Phip behave as tumor suppressors in Eμ-Myc driven lymphomas." (PMID 27982060, 2016). "For Sp3 and Phip, both sgRNAs lead to increased lymphoma onset compared to the Rosa26 cohort." (PMID 27982060, 2016). "We also noted considerable sequence heterogeneity at the Sp3 or Phip loci within any given lymphoma indicating that the tumors that arose were polyclonal in nature and thus unlikely to be due to rare integration events that inactivated a tumor suppressor locus." (PMID 27982060, 2016). "The restoration of SP3 expression did not suppress the cancer phenotype of lymphoma cells from Methylated person C or person E cells in the soft agar assay, suggesting that the cancer state, once established, cannot be reversed." (PMID 36618443, 2021).
pneumonia (3 papers, 2019 to 2021). An acute, acute and chronic, or chronic inflammation focally or diffusely affecting the lung parenchyma, caused by an infection in one or both of the lungs (by bacteria, viruses, fungi, or mycoplasma.). "The lungs of mice infected with PR8, vehicle treated, and then Sp3 infected showed a worsened histopathology, i.e., strong peribronchiolitis and alveolitis with several patches of pneumonia and inflammatory mononuclear infiltrates (bottom middle)." (PMID 31064834, 2019). "In conclusion, the antibiotic-resistant Sp3 strain induced effective pneumonia when animals had been previously exposed to experimental flu." (PMID 31024555, 2019). "Mice infected with Sp3 alone showed lung damage that included bronchial plugs filled with neutrophils, marked peribronchiolar and perivascular neutrophilic inflammation, and patches of pneumonia consisting of both interstitial and alveolar neutrophilic infiltrates (bottom left)." (PMID 31064834, 2019).
sarcoma (3 papers, 2013 to 2022). A usually aggressive malignant neoplasm of the soft tissue or bone. "In another study, SP3 is described as a driving force for cancer metastasis in sarcomas." (PMID 36553500, 2022).
astrocytoma (2 papers, 2016 to 2017). "However the slope of the fit is inversed in the two groups of tumors; that is, MAOB positively correlated with Sp3 levels in the astrocytoma and aberrant GBM and is negatively correlated as in the case of the 16 mainstream GBM, hence the opposing slopes of the black and red fitted lines." (PMID 26689994, 2016).
breast tumor (2 papers, 2018 to 2021). "We probed the mRNA level of SP3 in normal and breast tumor tissues and observed that expression of SP3 was upregulated in breast tumors (n = 20) relative to normal breast tissues (n = 20)." (PMID 30386180, 2018).
endometriosis (2 papers, 2025 to 2026). The growth of functional endometrial tissue in anatomic sites outside the uterine body. "Similarly, in JAR cells co-cultured with gestational epithelial endometriosis, NR2F2 and IGF2 were upregulated, whereas MDFI, SP3, and RDH10 were downregulated." (PMID 42282918, 2026).
gastric adenocarcinoma (2 papers, 2005 to 2016). "A recent report has demonstrated that the oxidative stress incurred by H2O2 increases the VEGF-A gene expression by increasing the binding of transcriptional factors Sp1 and Sp3 to proximal GC-rich motif in AGS human gastric adenocarcinoma cells." (PMID 15811836, 2005). "Oxidative stress has been shown to increase VEGF production by activating VEGF promotor, located between -449 and -1, in macrophages, or through enhancing the binding of Sp1 and Sp3 transcription factors to proximal GC-rich motifs at -73/-66 and -58/-52 in gastric adenocarcinoma cells." (PMID 27783650, 2016).
Hypertension (2 papers, 2016 to 2023). The presence of chronic increased pressure in the systemic arterial system. "Tamoxifen-induced deletion of endothelial Sp1 and Sp3 in male mice decreases the serum nitrite/nitrate level, impairs endothelium-dependent vasodilation, and causes hypertension and cardiac remodeling." (PMID 37735515, 2023). "Specific targeting of superoxide and/or Sp3 may provide a selective and better therapeutic target to combat oxidative stress and/or its mediated effects responsible for hypertension and associated cardiovascular diseases." (PMID 28203527, 2016). "Here, we show that targeted deletion of endothelial Sp1 and Sp3 in male mice leads to a reduction in serum nitrite/nitrate levels, a disruption in endothelium-dependent vasodilation, and the onset of hypertension and cardiac remodeling." (PMID 37735515, 2023). "This study demonstrated that Sp1/Sp3 protect against endothelial dysfunction and hypertension, enhancing our understanding of the functions of Sp1 and Sp3." (PMID 37735515, 2023). "Here, the authors show deletion of endothelial Sp1 and Sp3 leads to a disruption in endothelium-dependent vasodilation and the onset of hypertension, which abolishes the beneficial actions of captopril." (PMID 37735515, 2023). "In the endothelium of mesenteric arteries from patients with hypertension, Sp1 and Sp3 were notably downregulated when compared to those from healthy individuals." (PMID 37735515, 2023). "Given the critical roles of Ang II, endothelin-1 (ET-1), and H2O2 in hypertension and vascular diseases, we aimed to explore whether they regulate the expression of Sp1 and Sp3 in endothelial cells." (PMID 37735515, 2023). "Indeed, endothelial Sp1 and Sp3 were responsible for the anti-hypertension and anti-endothelial dysfunction effects of captopril, which is the major finding of this study." (PMID 37735515, 2023). "Ang II, ET-1, or H2O2-mediated Sp1/Sp3 downregulation in endothelial cells may be a common mechanism in the early development of hypertension." (PMID 37735515, 2023). "To determine whether Sp1 and Sp3 are involved in the pathogenesis of endothelial dysfunction and hypertension, we detected their expression in the endothelium of mesenteric arteries from hypertensive patients and hypertensive mouse arteries." (PMID 37735515, 2023). "Therefore, the reduction of Sp1 and Sp3 expression may crucially contribute to endothelial dysfunction and hypertension." (PMID 37735515, 2023). "Thus, Sp1/Sp3 may be involved in the pathogenesis of hypertension." (PMID 37735515, 2023). "In this study, we demonstrated that endothelial-specific Sp1/Sp3 deletion resulted in endothelial dysfunction and hypertension, and that captopril, an ACE inhibitor and traditional antihypertensive drug, exerted part of its pharmacological effect by modulating Sp1/Sp3 levels in endothelial cells." (PMID 37735515, 2023).
influenza (2 papers, 2019). An acute viral infection of the respiratory tract, occurring in isolated cases, in epidemics, or in pandemics; it is caused by serologically different strains of viruses (influenzaviruses) designated A, B, and C, has a 3-day incubation period, and usually lasts for 3 to 10 days. "Since infection by influenza virus induces major changes in lung integrity and immune cell populations, we investigated the immunomodulatory impact of flagellin on post-flu respiratory infections by the antibiotic-resistant Sp3 strain." (PMID 31024555, 2019). "In order to test the efficacy of an antibiotic+flagellin combination treatment in the post-influenza Sp3 superinfection model, mice were treated with AMX alone, flagellin FliCΔ174−400 alone, or a combination of both compounds 12 h after the bacterial infection." (PMID 31024555, 2019).
leukemia (2 papers, 2012 to 2020). A malignant (clonal) hematologic disorder, involving hematopoietic stem cells and characterized by the presence of primitive or atypical myeloid or lymphoid cells in the bone marrow and the blood. "Rothem et al26 have reported that reduced expression of transcription factors as CREB1, ATF1, USF1, FOS, JUN, Sp3, and Sp1 is responsible for a major decrease in RFC mRNA expression in the CCRF‐CEM and derived human leukemia cell lines." (PMID 32614991, 2020). "For the leukemia dataset, among the 10 top-ranked genes, two genes (ZYX and CCND3) are cancer ones, five (APLP2, CD33, SP3, CD63, PSME1) and one other genes (CST3) are directly or indirectly associated with cancer genes, respectively." (PMID 22830977, 2012).
Obesity (2 papers, 2021 to 2022). Accumulation of substantial excess body fat. "The ‘A’ allele of the SNP rs4783961 has been shown to influence the concentration of CETP mass in plasma by producing binding motifs for transcription factor SP3, which modulates CETP promoter activity, but studies examining the association of rs4783961 with obesity traits are limited." (PMID 35807893, 2022).